COA6 (cytochrome c oxidase assembly factor 6)
Description:
Involved in the maturation of the mitochondrial respiratory chain complex IV subunit MT-CO2/COX2. Thereby, may regulate early steps of complex IV assembly. Mitochondrial respiratory chain complex IV or cytochrome c oxidase is the component of the respiratory chain that catalyzes the transfer of electrons from intermembrane space cytochrome c to molecular oxygen in the matrix and as a consequence contributes to the proton gradient involved in mitochondrial ATP synthesis. May also be required for efficient formation of respiratory supercomplexes comprised of complexes III and IV.
Synonyms: C1orf31; CEMCOX4; MC4DN13
Tractability: PROTAC: ubiquitination databases record sites on it; its protein half-life has been measured.
Gene: Protein-coding gene on chromosome 1 (234,373,456 to 234,385,080, forward strand). Ensembl gene ENSG00000168275.
Subcellular location: Mitochondrion intermembrane space
Subcellular location (Human Protein Atlas): Mitochondria; Nucleoplasm
Pathways (Reactome):
Protein localization: Mitochondrial protein import
Gene Ontology:
Molecular function: copper ion binding; protein binding; protein-disulfide reductase activity; RNA binding
Biological process: mitochondrial respiratory chain complex IV assembly; respiratory chain complex IV assembly
Cellular component: mitochondrial intermembrane space; mitochondrion
Genetic constraint (gnomAD): Loss-of-function variants: 9 observed, 14.75 expected, observed/expected ratio (o/e) 0.61, 90% interval 0.37 to 1.07. The upper end of that interval is the gene's LOEUF score, 1.07, which puts it in group 4 of 6, group 1 being the genes least tolerant of losing a copy. Missense variants: 186 observed, 149.1 expected, observed/expected ratio (o/e) 1.25, 90% interval 1.11 to 1.41. Synonymous variants: 67 observed, 56.11 expected, observed/expected ratio (o/e) 1.19, 90% interval 0.98 to 1.46.
Gene-disease validity (ClinGen):
ClinGen rates the evidence that COA6 causes each of these diseases.
mitochondrial disease (autosomal recessive): Definitive.
Homologues: Orthologues: chimpanzee COA6 (99% identical), macaque COA6 (95% identical), dog COA6 (50% identical), rat Coa6 (45% identical), mouse Coa6 (41% identical), tropical clawed frog coa6 (33% identical), zebrafish coa6 (27% identical), Drosophila melanogaster CG42376 (25% identical).
Diseases named in the same sentence as COA6 in open-access papers:
COA6 is named in the same sentence as 24 diseases in open-access papers, as found by Europe PMC text mining. Sharing a sentence is not in itself a finding about the gene and the disease. The quoted sentences say what the papers report.
hypertrophic cardiomyopathy (4 papers, 2018 to 2023). A condition in which the myocardium is hypertrophied without an obvious cause. "For example, patients with mutations in the SCO1, SCO2, and COA6 proteins suffer from hypertrophic cardiomyopathy owing to a defect in COX2 biogenesis which results in COX deficiency." (PMID 32977416, 2020). "In a separate study, a patient with W66R mutation in COA6 was identified with neonatal hypertrophic cardiomyopathy, muscular hypotonia, and lactic acidosis and a clear COX defect in fibroblasts." (PMID 32977416, 2020). "SCO1 patients suffer from hypertrophic cardiomyopathy, neonatal hepatopathy, and ketoacidotic comas, whereas mutations in COA6 cause fatal infantile cardioencephalomyopathy." (PMID 29381136, 2018). "A targeted next-generation sequencing study identified two pathogenic mutations of the COA6 protein, W59C and E87*, in a patient suffering from hypertrophic obstructive cardiomyopathy with a combined mitochondrial complex I and COX deficiency in the heart tissue and no defect in the fibroblasts." (PMID 32977416, 2020).
atherosclerosis (2 papers, 2023 to 2025). A disease characterized by the build-up of fatty material and calcium deposition in the arterial wall resulting in partial or complete occlusion of the arterial lumen. "Complementary GO/KEGG enrichment analyses showed that the COA6‐high group was significantly enriched in membrane‐related functions, including secretory granule formation and vesicle transport, and was involved in immunometabolic regulation via IL‐17, atherosclerosis and other signalling pathways." (PMID 40596639, 2025). "In the training dataset GSE97210, SLC31A1, ATP7A, SLC31A2, UBE2D1, CP and FDX1 were highly expressed while LOXL2, COA6 and SOD1 were lowly expressed in the atherosclerosis group as showed in the bar charts." (PMID 37324184, 2023).
cardiomyopathies (2 papers, 2022 to 2025). "Coa6 is the only candidate directly involved with complex-IV assembly, mutations of which have been reported in cardiomyopathy cases." (PMID 41446135, 2025).
lung adenocarcinoma (2 papers, 2023 to 2024). A carcinoma that arises from the lung and is characterized by the presence of malignant glandular epithelial cells. "However, the role of COA6 in lung adenocarcinoma (LUAD) remains unknown." (PMID 36982777, 2023). "Cytochrome c oxidase assembly factor 6 (COA6), which functions as a metal chaperone to transport copper to complex IV during the OXPHOS process, plays a crucial role in the carcinogenesis of lung adenocarcinoma." (PMID 39132153, 2024).
lymph node metastasis (2 papers, 2023 to 2024). "In N (lymph node metastasis) stages, the COA6 mRNA expression was higher in N1/2/3 than in N0 groups (p < 0.05)." (PMID 36982777, 2023). "In tumor (the size of the tumor, lymph node metastasis, and distant metastasis) stages, the COA6 mRNA expression was higher in the II, III, and IV groups than the I group (p < 0.05)." (PMID 36982777, 2023).
amyloidosis (1 paper, 2021). A disorder characterized by the localized or diffuse accumulation of amyloid protein in various anatomic sites. "The MMSE‐correlated DEPs were mainly involved in amyloidosis (DNM1, UBR1, OPTN, FERMT2), CNS disorder (WIPF1) and energy metabolism (COA6, COX7C, PDPR) processes." (PMID 34528736, 2021).
breast carcinoma (1 paper, 2024). "COA6 overexpression was associated with clinicopathological parameters and unfavorable prognosis in breast cancer patients." (PMID 39132153, 2024). "The present investigation aimed to clarify COA6's expression profile and regulatory functions in breast cancer, as well as to unveil its underlying mechanisms." (PMID 39132153, 2024). "Furthermore, we demonstrated a causal role for COA6 in the regulation of biological behaviors of breast cancer cells by establishing stable cell lines with overexpressed and silenced COA6." (PMID 39132153, 2024). "Further clinical investigation is warranted to provide substantial insights into the role of COA6 in mitochondrial metabolism, particularly in breast cancer." (PMID 39132153, 2024). "The differential gene expression analysis revealed significant overexpression of COA6 mRNA in breast cancer tissue specimens." (PMID 39132153, 2024). "Initially, our findings revealed a significant upregulation of COA6 in breast cancer, as evidenced by an analysis of the TCGA database and tissue microarrays." (PMID 39132153, 2024). "Collectively, this study reveals an overt tumorigenic role for COA6 in breast cancer and sheds light on its potential mechanisms, offering valuable therapeutic targets for breast cancer therapy." (PMID 39132153, 2024). "Out of the 125 breast cancer cases studied, 15 (12%) exhibited low COA6 expression, while 110 (88%) showed high COA6 expression." (PMID 39132153, 2024). "COA6 is considered a significant player among these genes, with its mRNA levels notably elevated in breast cancer tissues and this overexpression directly impacting patient survival." (PMID 39132153, 2024). "The current study revealed firstly that COA6 is significantly overexpressed in breast cancer tissues." (PMID 39132153, 2024). "KEGG pathway enrichment analysis revealed a significant enrichment of differentially expressed genes with positive correlations with COA6 in OXPHOS signaling among breast cancer cases." (PMID 39132153, 2024). "Subsequent assessment of the TCGA database using DESeq2/edgeR confirmed a significant upregulation of COA6 in the breast cancer group." (PMID 39132153, 2024). "Immunohistochemical (IHC) analysis further investigated the protein expression and clinical relevance of COA6 in breast cancer." (PMID 39132153, 2024). "The data revealed elevated COA6 mRNA and protein amounts in breast cancer cells." (PMID 39132153, 2024). "Additionally, this study confirms that depleted COA6 downregulates key subunits of the OXPHOS complex in breast cancer cells, thereby impeding cancer cell proliferation." (PMID 39132153, 2024). "COA6 has significant effects on breast cancer, and decreasing its levels may reduce OXPHOS, ultimately inhibiting breast cancer cells." (PMID 39132153, 2024). "However, this work unveils an oncogenic role for COA6 in breast cancer." (PMID 39132153, 2024). "Notably, functional enrichment analysis indicated COA6 might be involved in breast cancer progression by modulating oxidative phosphorylation (OXPHOS)." (PMID 39132153, 2024). "Therefore, COA6 increases the migratory and invasive capabilities of breast cancer cells." (PMID 39132153, 2024). "COA6 mRNA and protein amounts were assessed in MDA-MB-231, HCC1937, SK-BR-3 and MCF-7 (breast cancer cells) comparatively to the noncancerous breast ductal epithelial MCF10A cell line using qRT-PCR and immunoblot." (PMID 39132153, 2024).
cardiac hypertrophy (1 paper, 2022). "Thus, a COA6 mutation, W66R, in humans is associated with mitochondrial complex IV deficiency in the heart and subsequently causes cardiac hypertrophy." (PMID 35277059, 2022).
colon cancer (1 paper, 2022). "FKBP4 controls mitochondrial respiration via modulating COA6-mediated biogenesis and activity of mitochondrial complex IV, thereby regulating 5-fluorouracil sensitivity in colon cancer." (PMID 35981890, 2022).
hepatocellular carcinoma (1 paper, 2024). A malignant tumor that arises from hepatocytes. "Similarly, COA6 upregulation was detected in hepatocellular carcinoma (HCC) tissues, with significantly associations with poor survival outcomes." (PMID 39132153, 2024).
neuroblastoma (1 paper, 2022). Neuroblastoma (NB) is the most common solid, extracranial childhood tumor. "We probed COA3, COA6, and COA129 neuroblastoma PDX cells with anti-human CD111, CD112, syndecan, and HVEM and found that each PDX expressed all four viral receptors." (PMID 35159029, 2022).
ovarian carcinoma (1 paper, 2024). A malignant neoplasm originating from the surface ovarian epithelium. "PKM2, MRPS12, NDUFC2, HPDL, MRPL14, COA6 and RNF144B were significantly upregulated in ovarian cancer tissues than in normal tissues (P < 0.05), while RPL23, FGFR1OP2, CAPN10, ALDH1L1 and ACSM1 were significantly down-regulated (P < 0.05)." (PMID 39478854, 2024). "PKM2, MRPS12, NDUFC2, HPDL, MRPL14, COA6 and RNF144B were significantly upregulated in ovarian cancer, but the down-regulation of NDUFC2, HPDL, MRPL14, COA6 and RNF144B was associated with poor prognosis in patients with ovarian cancer." (PMID 39478854, 2024).
pancreatic adenocarcinoma (1 paper, 2025). "In our analysis of the impact of COA6 overexpression on the pancreatic cancer immune microenvironment, we used the EaSIeR method to evaluate immune responses based on bulk RNA‐seq data from pancreatic adenocarcinoma (PAAD) patients in the TCGA database." (PMID 40596639, 2025).
pancreatic cancer (1 paper, 2025). "Overall, these findings highlight that COA6 overexpression in pancreatic cancer is linked to a broad suppression of key immune markers, which could potentially hinder the effectiveness of immune checkpoint inhibitors." (PMID 40596639, 2025). "The proportion of early and late apoptotic cells was significantly elevated in the COA6 knockdown group, suggesting that COA6 suppresses apoptosis in pancreatic cancer cells." (PMID 40596639, 2025).
primary cardiomyopathy (1 paper, 2023). "Therefore, we ultimately identified four genes as differential CRGs shared by the three kinds of primary cardiomyopathy: COA6, FDX1, MAP2K1, and SLC31A1." (PMID 38085668, 2023).
prostate carcinoma (1 paper, 2024). A carcinoma that arises from epithelial cells of the prostate gland. "In prostate cancer, high COA6 expression enhanced OXPHOS and promoted tumor progression." (PMID 39132153, 2024). "According to previous studies, Adrb2 deletion in endothelial cells increases COA6 expression, enhances OXPHOS, and promotes prostate cancer progression." (PMID 39132153, 2024).
sarcoma (1 paper, 2022). A usually aggressive malignant neoplasm of the soft tissue or bone. "Such quantities of mIL-12 from the COA3 and COA6 have been shown to generate an immune response in a murine sarcoma model and suggest potential for an immune cell attack on COA3 and COA6." (PMID 35159029, 2022).
tumor (7 papers, 2021 to 2025). "Further spatial correlation analysis revealed that COA6 expression was positively associated with several key cell populations, including tumour epithelial cells, CAFs, macrophages and endothelial cells." (PMID 40596639, 2025). "This may explain the associations of COA6 expression with tumor stage and poorer overall survival in patients with elevated COA6 levels." (PMID 39132153, 2024). "These phenotypic changes were accompanied by pronounced activation of OXPHOS, linking elevated COA6 expression to advanced tumour stages and poorer overall patient survival." (PMID 40596639, 2025). "Spatial neighbourhood maps demonstrated substantial connectivity between CAFs with high COA6 expression and surrounding cell types, suggesting a potential role in tumour progression and intercellular communication." (PMID 40596639, 2025). "Specifically, our analysis identified COA6 as a key mitochondrial gene associated with OXPHOS and tumour aggression, demonstrating its potential as a prognostic biomarker and therapeutic target." (PMID 40596639, 2025). "These structural genomic variations further contribute to the observed differences in immune modulation and highlight the complex interplay between COA6 expression, tumour immunogenicity and immune evasion." (PMID 40596639, 2025). "In contrast, COA6 expression was relatively diminished in the tumour margins and in non‐tumoral regions, indicating potential functional compartmentalisation." (PMID 40596639, 2025). "These transcription factors functioned synergistically to promote the tumour‐supportive phenotype of COA6‐high CAFs." (PMID 40596639, 2025). "This revealed that changes in COA6 expression were closely aligned with the trajectory of tumour progression, with COA6‐high CAFs marking the initial phase of the cellular dynamic process." (PMID 40596639, 2025). "Immunohistochemical analysis from the Human Protein Atlas (HPA) database revealed markedly enhanced COA6 staining intensity in tumour tissues compared to normal controls, indicating significant upregulation at the protein level." (PMID 40596639, 2025). "Quantitative comparison of COA6 expression across annotated regions revealed that expression levels were significantly higher in tumour regions compared to both mixed and normal tissue areas (p < 0.001)." (PMID 40596639, 2025). "Cytolytic activity (CYT), a measure of the tumour's ability to initiate cytotoxic immune responses, also showed a marked decrease in the presence of high COA6 expression." (PMID 40596639, 2025). "Future studies should aim to elucidate the specific mechanisms by which COA6 regulates tumour metabolism and explore its potential as a therapeutic target to improve outcomes in PDAC patients." (PMID 40596639, 2025). "In the T (the size of the tumor) stages, the COA6 mRNA expression was higher in T2, T3, and T4 than in the T1 groups (p < 0.05)." (PMID 36982777, 2023). "COA6 expression was significantly elevated in tumour‐rich regions, and this pattern was consistently observed in an independent spatial transcriptomic data set, further confirming the tumour‐specific enrichment of COA6 expression." (PMID 40596639, 2025). "Given the importance of antigen presentation and immune cell adhesion in anti‐tumour immunity, these findings suggest that tumours with elevated COA6 expression may possess stronger capabilities for immune cell recruitment and interaction." (PMID 40596639, 2025). "This further indicates that COA6 overexpression disrupts the proper organisation of immune responses, preventing the formation of structures that support effective immune interactions and responses against the tumour." (PMID 40596639, 2025). "This suggests that COA6 may impair the cytotoxic response of immune cells, which is vital for the elimination of tumour cells." (PMID 40596639, 2025). "We next explored the relationship between COA6 expression and the tumour immune microenvironment." (PMID 40596639, 2025).